EXO1 (exonuclease 1)
Diseases named in the same sentence as EXO1 in open-access papers (continued):
Sharing a sentence is not in itself a finding about the gene and the disease.
cancer (continued). "We identified 15 highly connected hub genes in MEtan, including ABCA8, AFP, EGR3, EXO1, HMGA1, MT1X and VARS, which play roles as major regulators in cell-cycle regulation and cancer development." (PMID 27220887, 2016). "Surprisedly, in all 31 cancer types in TCGA except low‐grade glioma (LGG), EXO1 and E2F1 were consistently upregulated in tumor samples compared to normal samples, and the upregulation of expression of these two genes was statistically significant in 20 of these cancer types." (PMID 38544480, 2024). "However, EXO1 is also involved in the HR DDR pathway, and downregulation has been shown to sensitize cancer cells to cisplatin specifically through the HR pathway." (PMID 39001501, 2024). "The most frequently amplified genes across the pan-cancer atlas were BRIP1 (HDR, 8.04%), POLB (BER, 6.54%), MUS81 (HDR, 6.42%), NBN (HDR, 6.31%), and EXO1 (MMR, 6.26%), while the most frequently deleted genes were BRCA2 (HDR, 6.44%), XRCC2 (HDR, 6.38%), and CUL5 (NER, 6,28%)." (PMID 36081518, 2022). "Moreover, MEF2D binding activity to FANCD2, EXO1, and XRCC4 was significantly higher in cancer cells than in normal cells, and ARN3261 significantly reduced MEF2D binding activity to FANCD2, EXO1, and XRCC4 in cancer cells compared with normal cells." (PMID 35642638, 2022). "Unexpectedly, mutations in EXO1, encoding the only exonuclease genetically implicated in MMR, are not linked to familial cancer and cause a substantially weaker mutator phenotype." (PMID 34228493, 2021). "Our bioinformation analysis data shows that ZGRF1 expression also positively correlates with the mRNA levels of BRCA1 and EXO1, which are well known for PARPi targets, and higher expression of ZGRF1 predicts poor prognosis of patients in several types of cancer." (PMID 34552057, 2021). "Based on our findings, it appears highly probable that, as in the case of EXO1, mutations in the FAN1 gene will also not segregate with cancer." (PMID 34228493, 2021). "Our research revealed the relationship between the abnormal expression of EXO1 and malignant biological characteristics of HCC and might lead to the development of novel anti-cancer therapeutics for HCC treatment." (PMID 32626539, 2020). "The immunohistochemical staining results from HPA database indicated significantly higher positivity for AURKA, CCNB1, CCNF, and EXO1(Not found in HPA database) in cancer tissues than in adjacent normal tissues." (PMID 31087508, 2019). "Additionally, our analysis of chemokines revealed a strong positive correlation between EXO1 expression and CCL7, CCL13, and CCL18 in BRCA, OV, THCA, and UCEC, while a negative correlation was observed with CCL14 and CCL16 in most female-related cancers." (PMID 40433389, 2025). "Taken together, SIK2 inhibition decreases PARP enzyme activity and the expression of FANCD2, EXO1, and XRCC4, suggesting that the combination of a SIK2 inhibitor and PARP inhibitor has the potential to increase the magnitude and duration of PARP inhibitor activity in patients with different cancers." (PMID 35642638, 2022). "None of the cancers analyzed showed any significant down-regulation of EXO1." (PMID 35769911, 2022). "Furthermore, several lines of previous research have reported a negative relationship between the overexpression of EXO1 and the prognosis of various cancers." (PMID 34950206, 2021). "The expression of breast cancer 1, early onset (BRCA1), RAD51, bloom syndrome, RecQ helicase-like (BLM), flap-endonuclease 1 (FEN1), uracil-DNA glycosylase (UNG), damage-specific DNA binding protein 2 (DDB2) and exonuclease 1 (EXO1) were significantly suppressed after 24 h ZEA treatment." (PMID 24788721, 2014). "However, whether Exo1 is required to activate MMR-dependent DNA damage response (DDR) remains unknown, the conclusions of the Exo1 polymorphisms on cancer susceptibility studies were not consistent." (PMID 24810280, 2014).
tumor (57 papers, 2011 to 2025). "Disruption of the EXO1 gene resulted in heightened microsatellite instability in cells and increased tumor susceptibility in mice." (PMID 40433389, 2025). "In UCEC, clinical stage, primary therapy outcome, histological type, residual tumor and EXO1 were identified as independent risk factors." (PMID 40433389, 2025). "Together, our findings strongly suggest FEN1 and EXO1 to be useful as pharmaceutical targets for PARG-deficient tumor cells, as well as for the optimization of PARGi in precision oncology." (PMID 38360994, 2024). "EXO1 expression levels in the HCC tissues were associated with the tumor grades, alpha-fetoprotein (AFP) levels, and the tumor stages." (PMID 35769911, 2022). "The logistic regression analysis showed that EXO1 expression levels were associated with the clinical stages including T stages and histological stages, tumor status, and AFP levels." (PMID 35769911, 2022). "Abnormal activation of the cGAS-STING pathway due to the loss of MutLα-specific regulation of exonuclease 1 (Exo1) during DNA repair also facilizes the clearance of MMR deficient tumor cells." (PMID 35541922, 2022). "Several lines of evidence suggest that EXO1 is overexpressed in certain tumor cells and may serve as a candidate susceptibility gene for breast, ovarian, lung, and gastrointestinal cancers." (PMID 40433389, 2025). "EXO1 expression is correlated with various factors within the tumor immune microenvironment and may be associated with the sensitivity to anticancer drugs." (PMID 40433389, 2025). "The association of EXO1 with E2F suggests that it may modulate cell cycle dynamics, thereby influencing tumor growth." (PMID 39777332, 2024). "Hence, the increased dependence of PARG;BRCA2-deficient cells on EXO1/FEN1 function is also relevant in human tumor cells." (PMID 38360994, 2024). "In addition, several single nucleotide polymorphisms (SNPs) in the EXO1 gene are associated with tumor susceptibility in a variety of tumors including liver, gastric, ovarian, cervical, breast, and colorectal cancers as well as head and neck squamous cell carcinoma 17-25." (PMID 32626539, 2020). "EXO1, a key player in DNA end resection, has been shown to be overexpressed in several tumor types, including liver and lung cancers." (PMID 41323735, 2025). "Nevertheless, further investigation is required to elucidate the precise signaling pathway through which the EXO1 protein operates in DNA damage repair mechanisms and its involvement in tumor chemoresistance." (PMID 40433389, 2025). "The analysis revealed that EXO1 was significantly upregulated in tumor tissues versus normal tissues for BRCA, CESC, OV, THCA, UCEC, and UCS based on a combined dataset from the Genotype-Tissue Expression Project (GTEx) and TCGA (P < 0.001)." (PMID 40433389, 2025). "EXO1 exhibits multidimensional roles in female-related cancers as a prognostic biomarker and potentially influences tumor immune therapy responses and drug sensitivities." (PMID 40433389, 2025). "It has been reported that the increased expression of EXO1 is correlated with larger tumor size, increased tumor metastasis, suppressed immune cell infiltration and poor overall survival in LUAD patients." (PMID 40761262, 2025). "Our study revealed that DNA methylation levels in the EXO1 gene were significantly lower in tumor tissues compared to normal tissues in BRCA, UCEC, and THCA." (PMID 40433389, 2025). "The results showed that the tumor mass and volume were significantly reduced in the EXO1 knockdown group compared to the control group." (PMID 38279172, 2024). "Tumor related events such as DNA replication (EXO1, p = 0.036) and mismatch repair (POLD3, p = 0.011) were altered in primary and recurrent tumors." (PMID 39217365, 2024).
tumor (continued). "This differential expression suggests the potential of EXO1 as a drug target and provides insights into the biological mechanisms within the tumor microenvironment." (PMID 39777332, 2024). "Numerous studies have shown that specific antibodies binding to and degrading EXO1 can markedly inhibit the proliferation and survival of tumor cells." (PMID 39777332, 2024). "The varying levels of EXO1 expression in tumor diagnosis and treatment highlight its potential as a biomarker." (PMID 39777332, 2024). "Increased EXO1 expression levels were correlated with lymph node metastasis, pleural invasion, poor tumor differentiation, and advanced clinical stage." (PMID 39777332, 2024). "The analysis showed that EXO1 was statistically different in worse outcomes such as recurrence, living with tumor, and higher stage." (PMID 36971680, 2023). "And the EXO1 expression levels in tumor and adjacent normal tissues were examined and the prognostic value of EXO1 in LUAD patients was evaluated." (PMID 36971680, 2023). "Further study indicated that EXO1 is significantly up-regulated in worse clinicopathological features including recurrence, living with tumor, and higher stage." (PMID 36971680, 2023). "Our study demonstrated a potential relationship between EXO1 expression and tumor immune cell infiltration." (PMID 35769911, 2022). "Taken together, these results indicate that an intact nuclease activity is essential for EXO1 tumor suppressor functions." (PMID 35849338, 2022). "A nomogram model was constructed that included T stages, tumor status, pathologic stages, and EXO1 expression levels as parameters." (PMID 35769911, 2022). "The logistic regression analysis showed that the EXO1 expression levels positively correlated with T stage, tumor status, histologic grade, and AFP levels in the HCC tissues." (PMID 35769911, 2022). "Whole-exome sequencing of the tumor tissue of ISPIC20 revealed the presence of a homozygous, somatic mutation in EXO1, involved in DNA MMR and homologous recombination, which potentially underlies the higher mutational load observed in this sample." (PMID 35793870, 2022). "The EXO1 expression levels accurately distinguished tumor tissues from the adjacent peritumoral tissues with an AUC value of 0.971." (PMID 35769911, 2022). "Currently, the role of EXO1 in tumor immune cell infiltration, immune checkpoints, aberrant DNA methylation and genetic alterations, and diagnosis and prognosis in HCC has not been established." (PMID 35769911, 2022). "HCC patients with high- and low-EXO1 expression levels showed significant differences in the clinical T stages, pathological stages, tumor status, histological stages, alpha-fetoprotein (AFP) levels, overall survival (OS), and disease-specific survival (DSS)." (PMID 35769911, 2022). "CLEC1B, GYS2, and CYP2C8 were identified as tumor suppressors for the prognosis, however, EXO1 was determined to be an oncogene." (PMID 34950206, 2021). "Others have proposed that overexpression of the RRM2, GTSE1 and EXO1 genes in HNSCC have active roles in tumor progression and inhibition of the apoptosis pathway." (PMID 34231338, 2021). "While the expression levels of SEPT3, RAD51AP1, and EXO1 are higher in tumor-bearing patients, while ABHD14B is lower." (PMID 34646403, 2021). "EXO1 in hepatocytes was localized to the cytoplasm, and the average IHC score of EXO1 in tumor tissues was significantly higher than that in adjacent non-tumor tissues." (PMID 32626539, 2020). "Analysis of EXO1 prognosis from the TCGA database showed the overall survival rate and tumor-free survival rate of patients with high EXO1 expression were significantly lower than those of patients with low EXO1 expression." (PMID 32626539, 2020). "In our cohort, 4 patients were carriers of monoallelic predicted pathogenic variants in EXO1 or MSH3 genes, and one MSH3 carrier case harbored a tumor showing EMAST." (PMID 32635641, 2020).
tumor (continued). "Subsequently, the expression level of EXO1 was assessed by immunohistochemistry (IHC) in 10 pairs of tumor tissues and their adjacent non-tumor tissues." (PMID 32626539, 2020). "The expression of EXO1 in HCC tumor tissues was 27.2 times higher than that in peri-cancerous liver tissues." (PMID 32626539, 2020). "PCNA and FEN1 expression were significantly above tumor average in subtype 2, as were EXO1 and LIG1." (PMID 31857847, 2019). "Similar to DCLRE1A, Exo1 is also shown to be higher expressed in tumor tissues than that in the normal tissues." (PMID 27806724, 2016). "Although rather small (1.16-fold), we also observed different expression levels for EXO1 gene when compared tumor and adjacent mucosal tissues." (PMID 24484585, 2014). "Overall, only EXO1 was differentially expressed in our study group: significantly higher mRNA levels were observed in tumor tissues when compared with adjacent mucosal tissue (1.16-fold; P = 0.048)." (PMID 24484585, 2014). "Overexpression of EXO1 may disrupt cell cycle regulation, leading to uncontrolled cell proliferation and promoting tumor progression." (PMID 41154599, 2025). "In addition to its overexpression in tumor tissues, we observed that EXO1 showed a strong discriminatory ability between female-related tumors and normal tissues, except UCS." (PMID 40433389, 2025). "In addition, high EXO1 expression was associated with worse OS in UCEC patients with clinical stage I, tumor invasion >50%, open surgical approach, residual tumor classification of R0, and histological type of endometroid." (PMID 40433389, 2025). "Moreover, EXO1 mRNA expression was found to be elevated in tumor tissues compared to paracancerous tissues specifically in BRCA, THCA, and UCEC using data from TCGA database (P < 0.001)." (PMID 40433389, 2025). "Furthermore, we explored the correlations between EXO1 expression and the infiltration of 24 types of TIICs into the tumor microenvironment." (PMID 40433389, 2025). "Additionally, using the SurvivalMeth tool, significant differences in the expression of individual CpG site methylation of EXO1 were observed between tumor tissues and normal tissues in BRCA, UCEC, and THCA." (PMID 40433389, 2025). "In our study, the increased infiltration of Th2 cells in the context of EXO1 overexpression may contribute to an imbalance between Th1 and Th2 responses, enabling tumor cells to evade immunity." (PMID 40433389, 2025). "Concurrently, EXO1 overexpression may induce cell cycle dysregulation through the RB/E2F pathway, promoting tumor progression." (PMID 41154599, 2025). "It has been proposed that T-ALL/T-LBL patients may experience hypoxia in the tumor microenvironment due to aberrant expression of the EXO1 gene." (PMID 38464517, 2024). "The association of EXO1 with the FA pathway suggests that it may play a role in modulating the DNA damage response in LUAD, potentially influencing tumor cell survival under genotoxic stress." (PMID 39777332, 2024). "Notably, patients diagnosed with invasive pulmonary adenocarcinoma who exhibited elevated EXO1 expression levels exhibited increased lymph node metastasis, pleural invasion, poor tumor differentiation, and advanced clinical stage." (PMID 39777332, 2024). "Recent studies have underscored the significant role of EXO1 in tumor immune regulation." (PMID 39777332, 2024). "Moreover, one research suggested that the high expression of EXO1 was significantly correlated with aneuploidy, promoting tumor invasion in LUAD." (PMID 37325647, 2023). "Interestingly, EXO1 overexpression in tumor cells compared with corresponding normal ones is also observed in multiple human tissues, including liver, lung, pancreas and colon." (PMID 36255267, 2022). "EXO1 was overexpressed in the tumor tissues and serum samples of HCC patients." (PMID 35769911, 2022). "EXO1 expression levels correlated with tumor infiltration status of many immune cell types and may play a role in the response to immunotherapy in HCC patients." (PMID 35769911, 2022).
tumor (continued). "Moreover, an increased expression of EXO1 has been frequently observed in tumor tissues compared with normal breast ones." (PMID 36255267, 2022). "The overexpression of EXO1 in tumors may also increase the genetic instability and contribute to tumor initiation and progression through its involvement in recombinant events such as DSBs and telomere stabilization." (PMID 32626539, 2020). "In this study, we discovered that EXO1 expression is significantly higher in HCC tumor tissues." (PMID 32626539, 2020). "Cases with POLD2 and EXO1 expression above the tumor average had decreased survival by Log-rank." (PMID 31857847, 2019). "Finally, there were 133 of 140 tumor samples used for EXO1 protein expression analysis since 7 samples were missing in the process of IHC staining within the TMAs." (PMID 31777591, 2019). "By contrast, the EXO1 knockout rearrangement signature was dominated by medium-to-long tandem duplications emulating the alternative cohort of genomically unstable (but BRCA1-intact) tumours." (PMID 29717121, 2018). "Therefore, the higher expression of EXO1 in tumor tissues is consistent with this expectation." (PMID 40433389, 2025). "Additionally, high EXO1 expression levels were associated with poor PFI in female patients with THCA, as well as in THCA patients with left lobe of neoplasm location, no extrathyroidal extension, residual tumor classification of R0, and multifocal of primary neoplasm focus type." (PMID 40433389, 2025). "In patients with OV, higher EXO1 expression showed an inverse correlation with both International Federation of Gynecology and Obstetrics (FIGO) stage and the presence of residual tumor." (PMID 40433389, 2025). "They found that miR-519 inhibits the growth and survival of tumor cells via repressing the expression of proteins involved in DNA maintenance (including DUT1, EXO1, RPA2, and POLE4) and intracellular calcium homeostasis (ATP2C1 and ORAI1)." (PMID 37601663, 2023). "To elucidate the molecular mechanisms of EXO1 overexpression in HCC tumor tissues, we concentrated on the region 2 kb upstream of the transcription start site (TSS) of EXO1." (PMID 32626539, 2020). "These genes were distributed in multiple pathways, and some of them, such as MET (ranked 1st), PRKDC (ranked 8th), EXO1 (ranked 14th), and TM4SF1 (ranked 25th), have been reported to promote tumor cell proliferation." (PMID 32995120, 2020). "Comparing polymerase components across thirty-seven tumor types revealed a common subset with elevated transcriptional pattern typified by POLE2 and POLQ that included EXO1, MCM10, GINS2, CDT1, ORC6L, and BLM." (PMID 31857847, 2019). "EXO1 and NEIL3, are both involved in DNA damage response and replication fork progression under oncogenic stress, suggesting their role in promoting genomic instability during tumor progression." (PMID 41402347, 2025). "The interaction between EXO1 and PLK1 may facilitate enhanced cell proliferation and survival, thereby contributing to tumor aggressiveness." (PMID 39777332, 2024). "The expression level of EXO1 in our study was also significantly upregulated in primary SS samples from patients with metastasis compared to primary tumour samples from patients without metastasis." (PMID 39046429, 2024). "Our investigation also showed that EXO1 expression levels in the HCC tissues significantly correlated with the AFP levels, overall survival, disease-specific survival, clinical stages, and the tumor status." (PMID 35769911, 2022). "EXO1 matched FLUOROURACIL and CAPECITABINE, which mainly interfere with cell division and related RNA and protein synthesis, thus blocking the infinite proliferation ability of tumor cells." (PMID 35370655, 2022). "EXO1 expression levels showed a significant correlation with the race, AFP levels, DSS, OS, T stages, tumor status, histologic grades, and pathologic stages of the HCC patients." (PMID 35769911, 2022).